RPL41P1 (ribosomal protein L41 pseudogene 1)
Synonyms: formerly RPL41L2
Gene: Processed pseudogene on chromosome 20 (21,755,270 to 21,755,350, forward strand). Ensembl gene ENSG00000227063.
Diseases named in the same sentence as RPL41P1 in open-access papers:
RPL41P1 is named in the same sentence as 1 disease in open-access papers, as found by Europe PMC text mining. Sharing a sentence is not in itself a finding about the gene and the disease.
RPL41P1 shares sentences with these, for which no sentence is quoted: cancer (1 paper).